IL13RA2 (interleukin 13 receptor subunit alpha 2)
Diseases named in the same sentence as IL13RA2 in open-access papers (continued):
Sharing a sentence is not in itself a finding about the gene and the disease.
keloid (2 papers, 2023 to 2025). An irregularly shaped, elevated mark on the skin caused by deposits of excessive amounts of collagen during wound healing. "In keloids, the pro-proliferative effects occur via the decoy effect of IL13RA2 and reduced IL13RA2 leads to accelerated IL13-induced fibrosis through STAT6." (PMID 40663259, 2025). "To comprehensively study the role of IL-13RA2 in keloid pathogenesis, we also assessed the effect of IL13RA2 knockdown on the NF cell line NFb with siRNA (siRNA-IL13RA2)." (PMID 36757802, 2023). "Inhibiting the phosphorylation of STAT6 and ectopic overexpression of IL-13RA2 alleviate keloid fibrogenesis by inducing apoptosis and suppressing the migration, invasion, and collagen synthesis of myofibroblasts in vitro and in vivo." (PMID 36757802, 2023). "Ectopic expression of IL-13RA2 in keloid fibroblasts resulted in inhibition of STAT6 phosphorylation, cell proliferation, migration, invasion, extracellular matrix secretion, and myofibroblast marker expression, as well as an increase in apoptosis." (PMID 36757802, 2023). "Accordingly, quantitative analysis using gray values revealed that IL-13RA2 protein was downregulated in keloids compared with normal dermis (P < 0.05)." (PMID 36757802, 2023). "Collectively, this study elucidates the key role of IL-13RA2 in keloid pathology and inspires further translational research of keloid treatment concerning JAK/STAT6 inhibition." (PMID 36757802, 2023). "Further, we identified downregulation of IL-13RA2, a decoy receptor for IL-13, in keloid fibroblasts compared with fibroblasts from normal dermis." (PMID 36757802, 2023). "In the present study, we have found that IL-13 signaling and the downstream JAK/STAT6 pathway are activated by the downregulation of IL-13RA2 in keloids." (PMID 36757802, 2023). "Overall, the role of IL-13RA2 described here may enable a deeper understanding of the pathogenesis of keloids, which may in turn yield benefits for clinical transformation." (PMID 36757802, 2023). "Knockdown of IL13RA2 in NFs induced keloid-characteristic behaviors via JAK/STAT6 signaling." (PMID 36757802, 2023). "Moreover, IHC staining of keloids and normal dermis also showed that IL-13RA2 protein was decreased in keloids." (PMID 36757802, 2023). "Low expression of IL-13RA2 in patient-derived keloids was also verified by IHC." (PMID 36757802, 2023). "Furthermore, Western blot assay of NFs and NFs with Pearson’s correlation test of gray values revealed a negative correlation between IL-13RA2 expression and the p-STAT6/STAT6 ratio, suggesting an important role of IL-13RA2 in JAK/STAT6 activation in keloids." (PMID 36757802, 2023). "However, IL13RA2 mRNA was significantly lower in keloids than normal skins." (PMID 36757802, 2023). "Interestingly, reduced IL13RA2 expression was also identified in keloid fibroblasts, which are highly proliferative compared to normal skin." (PMID 40663259, 2025). "Finally, we chose AS1517499 to inhibit JAK/STAT6 in the patient-derived xenograft (PDX) model instead of directly regulating IL-13RA2 expression because there is still a lack of established animal models of keloids, and we believe organoid cultures and PDX will bridge current difficulties." (PMID 36757802, 2023).
lung adenocarcinoma (2 papers, 2015 to 2022). A carcinoma that arises from the lung and is characterized by the presence of malignant glandular epithelial cells. "IL13Rα2 positive expression was more frequently detected in lung adenocarcinoma than the other histological types (P = 0.01)." (PMID 26418721, 2015). "Human lung adenocarcinoma cell line A549 endogenously expresses moderate levels of IL13Rα1 with no detectable IL13Rα2 or IL4Rα." (PMID 35939683, 2022).
lung disease (2 papers, 2022 to 2025). "The interaction between CHI3L1 and IL‐13Rα2 could promote lung diseases associated with Hermansky–Pudlak syndrome." (PMID 34758182, 2022). "In Hermansky-Pudlak Syndrome lung disease, galectin-3 competes directly with TMEM219 to bind IL13RA2." (PMID 40663259, 2025).
lymph node metastasis (2 papers, 2016 to 2021). "The factors included in multivariate analysis were age, tumor size, tumor stage, lymph node metastasis, histologic nuclear grade, tumor necrosis, and immunohistochemical expression of IL13Rα2." (PMID 33917914, 2021). "IL-13Rα2 staining in training cohort was related to age (P = 0.029), depth of tumor invasion(P = 0.040), lymph node metastasis (P = 0.022) and TNM stage (P = 0.020)." (PMID 27351230, 2016).
metastatic malignant melanoma (2 papers, 2013 to 2019). "The present studies add to these observations by demonstrating that Tg Chi3l1/YKL-40 stimulates TGF-β1 in lungs with metastatic melanoma via an IL-13Rα2-dependent mechanism." (PMID 23972995, 2013).
Obesity (2 papers, 2021 to 2023). Accumulation of substantial excess body fat. "Further studies are warranted to investigate the biological importance of VSG- and allergen-induced changes in IL-13Rα2 expression in obesity." (PMID 36926031, 2023). "Higher expression of IL13RA2 supports the intergenerational transmission of metabolic sequelae (obesity/metabolic diseases) of a high-fat diet (HFD) from father to offspring." (PMID 34127924, 2021).
pulmonary hypertension (2 papers, 2014 to 2021). Increased pressure within the pulmonary circulation due to lung or heart disorder. "Two further genes on the X-chromosome, IL13RA1 and IL13RA2, play a role in the inflammatory processes activated in the hypertensive pulmonary circulation of some types of pulmonary hypertension." (PMID 34068984, 2021). "Potential conclusion: IL-13 promotes the development of pulmonary hypertension via an IL-13 - IL-13Rα2 - Arg2 pathway leading to an imbalance of NO homeostasis and increased muscularization of pulmonary arteries." (PMID 24739042, 2014). "IL13RA2 is upregulated in idiopathic PAH and in murine models of schistosomiasis-induced pulmonary hypertension." (PMID 34068984, 2021).
squamous cell carcinoma (2 papers, 2013 to 2019). A carcinoma arising from squamous epithelial cells. "Future studies will be conducted to determine if TGFβRI deletion facilitates IL-13Rα2 expression on squamous cell carcinomas." (PMID 23421960, 2013). "Conditional deletion of both TGFβRI and PTEN in the oral cavity of mice results in the formation of spontaneous squamous cell carcinomas in the head and neck area that display IL-13Rα2, a tumor antigen expressed in 33% of human HNSCCs." (PMID 23421960, 2013). "We have previously shown that cultured cells derived from the periorbital and perianal squamous cell carcinomas collected from another TGFβRI conditional knockout model can also express IL-13Rα2 and are sensitive to IL-13-PE treatment." (PMID 23421960, 2013). "Regardless of location, all squamous cell carcinomas displayed high expression of IL-13Rα2, making the mouse model ideal for studying targeted cytotoxin therapy against IL-13Rα2." (PMID 23421960, 2013).
Stroke (2 papers, 2022 to 2025). Sudden impairment of blood flow to a part of the brain due to occlusion or rupture of an artery to the brain. "Although limited literature has documented the associations between IL-13RA2 and stroke, it is generally understood that IL-13RA2 can be upregulated by pro-inflammatory factors such as TNF-α and IL-1β." (PMID 40474979, 2025). "Because of this reputed role, along with its limited expression in the stroke brain and the lack of clarity regarding its biological role, we did not examine the role of IL-13Rα2 in IL-13 signaling in the present study." (PMID 35578342, 2022).
angiosarcoma (1 paper, 2025). A malignant tumor arising from the endothelial cells of the blood vessels. "In contrast, IL-13Rα1 expression was limited in the angiosarcoma cell line, indicating a distinct pattern of high IL-13Rα2 and low IL-13Rα1 expression in angiosarcoma." (PMID 40855097, 2025). "IL-13Rα2 staining was observed not only in endothelial-like tumor regions but also in poorly differentiated angiosarcoma cells." (PMID 40855097, 2025). "We next detected high IL-13 receptor α2 (IL-13Rα2) expression in angiosarcoma cell lines and patient samples compared to other cell types and benign vascular tumors." (PMID 40855097, 2025). "IL13RA2 mRNA expression was significantly higher in angiosarcoma tumors (n = 12) compared to normal tissue controls (n = 6)." (PMID 40855097, 2025). "Functional studies showed that IL-13 promotes angiosarcoma cell proliferation, an effect mediated primarily through IL-13Rα2." (PMID 40855097, 2025). "On the other hand, we observed markedly higher IL-13Rα2 expression in angiosarcoma cell lines relative to any other examined cell types." (PMID 40855097, 2025). "To verify our findings in clinical samples, we next performed section staining on patient-derived angiosarcoma samples to examine the protein expression levels of IL-13Rα2." (PMID 40855097, 2025). "Immunohistochemical analysis corroborated the overexpression of IL-13Rα2 in angiosarcoma specimens compared to hemangiomas." (PMID 40855097, 2025). "We first reanalyzed transcriptomic data from a published angiosarcoma cohort and found IL13RA2 mRNA elevated in angiosarcoma versus normal tissue." (PMID 40855097, 2025). "In this study, we first reanalyzed transcriptomic data from a previously published angiosarcoma cohort and confirmed that IL13RA2 expression is elevated in angiosarcoma tumors compared to normal tissues." (PMID 40855097, 2025). "Further flow cytometry analysis confirmed these findings at the protein level, revealing higher IL-13Rα2 signals in angiosarcoma cells compared to A431 cells, consistent with our QPCR results." (PMID 40855097, 2025). "The effect was inhibited by siRNA-mediated knockdown of IL13RA2 or neutralizing antibodies against IL-13, suggesting the impact of IL-13/IL-13Rα2 axis in the angiosarcoma proliferation." (PMID 40855097, 2025). "Based on these expression analyses, we proceeded to investigate the effects of IL-13 and its receptors in angiosarcoma to further characterize their functional significance using MO-LAS-B cells which showed the highest expression of IL-13Rα2 in our QPCR analysis." (PMID 40855097, 2025). "This study showed remarkably high expression of IL-13Rα2 in the angiosarcoma cell line MO-LAS-B." (PMID 40855097, 2025). "Notably, angiosarcoma cell lines exhibited higher expression of IL-13Rα2 compared to other cell types, including immune cells and skin fibroblasts." (PMID 40855097, 2025).
bone sarcoma (1 paper, 2017). A sarcoma that arises from the bone. "GD2, IL-13Ra2, B7H3, and ErbB2 have been identified as potential targetable tumor antigens on solid tumors, including bone sarcomas and Ewing’s family tumors." (PMID 29029499, 2017).
brain glioma (1 paper, 2017). A malignant glioma that involves the brain. "Pep-1, a cell-penetrating peptide, could cross the BBTB and target the brain glioma via IL-13Rα2-mediated endocytosis." (PMID 28933201, 2017).
chordoma (1 paper, 2025). Chordomas are rare malignant tumors arising from embryonic remnants of the notochord in axial skeleton. "In addition to the well‐known chordoma biomarkers (LGALS3 and TBXT), the heatmap also revealed IGKV2, IL13RA2, RAB3B, and MAPK3 highly expressed in chordoma." (PMID 40135815, 2025).
choroid plexus papilloma (1 paper, 2013). "Interestingly, four specimens of canine choroid plexus papilloma samples (CPP) were noticeably enriched in IL-13RA2." (PMID 24147065, 2013).
choroid plexus tumors (1 paper, 2013). "Interestingly, canine choroid-plexus tumors contained high amounts of immunoreactive IL-13RA2; human choroid plexus tumors were not investigated in the current study and further examinaion is warranted." (PMID 24147065, 2013).
cutaneous T-cell lymphomas (1 paper, 2025). "However, dupilumab has also been associated with the “unmasking” of undiagnosed cutaneous T-cell lymphomas, driven by increased IL-13Rα2 signaling activating tumor proliferation and immune evasion, resulting in generalized lymphadenopathy and B-symptoms after initiation of dupilumab." (PMID 41216297, 2025).
depression (1 paper, 2020). "The allele A of the intronic variant rs2248440, associated with higher severity of depression, decreases the expression of the neighboring gene IL13RA2 in the putamen, according to GTEx." (PMID 33193575, 2020). "The variant rs6318 also regulates the expression level of IL13RA2 in the putamen; it is only polymorphic in the cohort under study but was previously associated with a number of phenotypes relevant to the pathogenesis of depression and to effects of psychotropic drugs." (PMID 33193575, 2020). "Although IL13RA2 is known to be implicated mainly in cancer, its ligand IL-13 regulates inflammation, so this gene could also play a part in increased inflammation seen in patients with depression." (PMID 33193575, 2020). "This connection could be the key to the observed immune system abnormalities strongly associated with depression and suggests a possibility of an interaction between HTR2C and IL13RA2." (PMID 33193575, 2020).
eczema herpeticum (1 paper, 2025). "Due to its activity against S. aureus and HSV-1 together with its ability to enhance IL13RA2 expression and suppress Th2 cytokine secretion, R7 is an attractive candidate for the treatment of AD, where these pathogens are major disease drivers and HSV-1 infection can lead to eczema herpeticum." (PMID 40461723, 2025).
eosinophilia (1 paper, 2023). "We show that our model of chronic respiratory HDM challenge resulted in the expected robust induction of murine peribronchial inflammation, airway mucus production and eosinophilia, increased serum IgE and lung expression of mucins, Tgfb1, and Il13ra2, regardless of surgery status." (PMID 36926031, 2023).
ganglioneuroma (1 paper, 2018). A benign neuroblastic tumor of the sympathetic nervous system that occurs in childhood. "Interestingly, all of the 2 ganglioneuroma (benign) and 6 neurofibroma (benign) that were present in the microarray were positive for IL13Rα2 expression." (PMID 29304038, 2018).
HCMV infection (1 paper, 2020). "In particular, HCMV infection led mainly to the over-expression of CCL2, CCL3, CCL11, CXCR4, IL-1β, IL13, MMP1, MMP3, MMP9 and MMP13, SERPINA1, TNFα, and BMP7, and the gradual and constant downregulation of IL13RA2 (up to almost 800-fold at 14 days p.i.)." (PMID 32899126, 2020).
hepatic granuloma (1 paper, 2015). A granuloma located in the liver. "Merge in white were demonstrated co-expression of IL-13Rα2 and CD68 at the same position of egg-induced hepatic granuloma (white)." (PMID 26317423, 2015).
Hypertension (1 paper, 2021). The presence of chronic increased pressure in the systemic arterial system. "Since phosphorylation of JAK2 was regulated by IL13Rα2, we tried to screen a novel JAK2 inhibitor from the FDA-approved drug library and selected telmisartan, a clinically used medicine against hypertension, as one of the strongest candidates." (PMID 33917914, 2021).
metastatic prostate carcinoma (1 paper, 2023). A carcinoma that arises from the prostate gland and has spread to other anatomic sites. "Our results agree with previous studies, which demonstrated that the expression of IL-13Rα2 is high in tumorigenic and metastatic prostate cancer cells." (PMID 36830725, 2023).
nematode infection (1 paper, 2013). "It is known that IL-13 activation of STAT6 during nematode infection increases the expression of IL-13Rα2, 5-HT2A, and arginase I in WT." (PMID 23536877, 2013).
neuroectodermal tumors (1 paper, 2019). "GD2 is known to be expressed on neuroectodermal tumors and is, besides IL13RA2 and mesothelin, one of the few CAR-T cell targets to have produced solid tumor regression." (PMID 31500597, 2019).
neurofibroma (1 paper, 2018). An intraneural or extraneural neoplasm arising from nerve tissues and neural sheaths. "The tumor from neurofibromas and schwannomas also express the bands corresponding to glycosylated and non-glycosylated forms of IL13Rα2." (PMID 29304038, 2018).
peripheral nerve tumors (1 paper, 2018). "Investigation by immunohistochemistry (IHC) on an additional 4 peripheral nerve tumors from the Pennsylvania State University core facility indicated that all of them were also positive for IL13Rα2." (PMID 29304038, 2018).
pulmonary TB (1 paper, 2016). "To validate our results in human TB patients, we here determined the association of distinct variants of the IL4, IL13, IL4RA, IL13RA1, and IL13RA2 genes with cavity formation in a large Ghanaian cohort of HIV-negative individuals with newly diagnosed pulmonary TB." (PMID 26977119, 2016).
retinal degeneration (1 paper, 2025). Degeneration of the retina. "In the context of retinal degeneration, IL13Rα2 expression is induced by photosensitization of N-retinylidene-N-retinylethanolamine (A2E), which triggers telomere dysfunction and accelerates RPE senescence." (PMID 41205411, 2025).
skin inflammation (1 paper, 2019). "The scratch signal exacerbates skin inflammation and conversely upregulates IL-13Rα2 expression, which may suppress excess IL-13 activity caused by the decoy function of IL-13Rα2 in keratinocytes." (PMID 31284553, 2019).
staphylococcal infection (1 paper, 2024). An infection caused by Staphylococcus. "The role of IL-13RA2 and IL-17D in bacterial pathogenesis has not been well delineated, but the higher levels of these cytokines in staphylococcal infections suggest that the immune mediators are dependent upon the type of infecting microorganism." (PMID 39770689, 2024).
systemic sclerosis (1 paper, 2015). A chronic disorder, possibly autoimmune, marked by excessive production of collagen which results in hardening and thickening of body tissues. "In addition to polymorphisms in IL13, a polymorphism in IL13Rα2 associated with systemic sclerosis in individuals of European ancestry occurs with higher frequency in individuals of African ancestry." (PMID 26540410, 2015). "Mutations in IL13Rα2, a decoy receptor that serves as an off-signal for IL13, are associated with systemic sclerosis." (PMID 26540410, 2015).
triple-negative breast carcinoma (1 paper, 2025). An invasive breast carcinoma which is negative for expression of estrogen receptor (ER), progesterone receptor (PR), and human epidermal growth factor receptor 2 (HER2). "We sought to define the role of IL13RA2 in triple-negative breast cancer growth and metastasis, with an emphasis on breast-to-brain metastasis." (PMID 40663259, 2025). "Our data suggest that inhibition of IL13RA2, though promising in other tumor contexts, may be deleterious in metastatic triple-negative breast cancer." (PMID 40663259, 2025).